MYBPC3 (myosin binding protein C3)
Diseases named in the same sentence as MYBPC3 in open-access papers (continued):
Sharing a sentence is not in itself a finding about the gene and the disease.
hypertrophic cardiomyopathy (continued). "A study published earlier this year by Seeger and colleagues made use of genome-editing techniques to create isogenic iPSC lines from patients with heterozygous mutations in the myosin-binding protein C3 (MYBPC3), which is deemed as the underlying cause of hypertrophic cardiomyopathy (HCM)." (PMID 31783680, 2019). "Mutations in MyBPC3 are present in 15% of our hypertrophic cardiomyopathy families." (PMID 20433692, 2010). "Mutations in MYBPC3 encoding myosin binding protein C belong to the most frequent causes of hypertrophic cardiomyopathy (HCM) and may also lead to dilated cardiomyopathy (DCM)." (PMID 18957093, 2008). "Nevertheless, one can argue that, for example, correcting the faulty version of the MYBPC3 gene that causes hypertrophic cardiomyopathy in fetus might help in the selection of the healthy embryos for implantation as a potential therapeutic intervention to treat monogenic inherited disorders." (PMID 33926574, 2021). "Furthermore, using a single gene model, Meurs & Kuan evaluated the methylation of the CpGs within the exon regions of the skeletal muscle isoform of the myosin binding protein C gene (MYBPC2) and cardiac myosin binding protein C gene (MYBPC3), a common causal gene for hypertrophic cardiomyopathy." (PMID 26701604, 2015). "Here, to study the pathogenesis of hypertrophic cardiomyopathy, we created a MYBPC3 knockout (KO) model using human induced pluripotent stem cell-derived cardiomyocytes (hiPSC-CMs)." (PMID 41158753, 2026). "Hypertrophic cardiomyopathy (HCM) is mainly driven by mutations in genes encoding sarcomeric proteins, e.g. myosin heavy chain (MYH7) and myosin binding protein C3 (MYBPC3)." (PMID 40207041, 2025). "MYBPC3 is a structural cardiomyopathy gene and represents the gene most frequently involved in hypertrophic cardiomyopathy (HCM)." (PMID 39940965, 2025). "A study conducted in a mouse model of hypertrophic cardiomyopathy (HCM) found that a single mutation in the MYBPC3 gene, encoding the myosin-binding protein C (cMyBP-C) protein, resulted in low cMyBP-C mRNA expression." (PMID 40862762, 2025). "Hypertrophic cardiomyopathy (HCM) is the most common known cause of sudden cardiac arrest in young adults and athletes, most frequently resulting from pathogenic variants in MYBPC3." (PMID 40118058, 2025). "Tenaya Therapeutics’ TN-201, designed to target MYBPC3 in hypertrophic cardiomyopathy, has demonstrated successful vector delivery and transgene expression in cardiac tissue." (PMID 40465697, 2025). "Structural disorders include hypertrophic cardiomyopathy (HCM), the most prevalent cause, accounting for 35% of confirmed cases in the U.S., characterized by mutations in genes like MYH7, MYBPC3, and TNNT2." (PMID 40724525, 2025). "Genome editing has also shown potential in addressing genetic conditions such as hypertrophic cardiomyopathy (HCM), which is often associated with MYBPC3 gene mutations." (PMID 39768189, 2024). "This phenomenon, recently described as a stochastic allelic expression in DCM, has been reported in hypertrophic cardiomyopathy patients with variants in myosin heavy chain 7 (MYH7) and myosin-binding protein C3 (MYBPC3)." (PMID 37723491, 2023). "For example, myosin-binding protein C3 (MYBPC3) gene appear to influence endurance and performance among elite athletes, although certain variants have been associated with hypertrophic cardiomyopathy." (PMID 38260814, 2023). "Transfer of the MYBPC3 gene elicited a 2.6-fold increase in the quantity of MYBPC3 messenger RNA in hypertrophic cardiomyopathy cells." (PMID 37445689, 2023). "Hypertrophic cardiomyopathy (HCM) is the most prevalent monogenic heart disease, commonly caused by pathogenic MYBPC3 variants, and a significant cause of sudden cardiac death." (PMID 36835444, 2023).
hypertrophic cardiomyopathy (continued). "Tenaya Therapeutics has received fast track designation for a phase 1b clinical trial for MYBPC3 gene replacement therapy for hypertrophic cardiomyopathy (NCT05836259), utilizing an optimized AAV9 vector to package the full-length MYBPC3 gene." (PMID 38665939, 2023). "Hypertrophic cardiomyopathy (HCM) is the most prevalent monogenic heart disease, commonly caused by truncating variants in the MYBPC3 gene." (PMID 33532905, 2021). "We reported that a Korean family presented different cardiomyopathies, such as idiopathic RCM and hypertrophic cardiomyopathy (HCM), caused by the same MYBPC3 mutation in different individuals." (PMID 33803538, 2021). "Hypertrophic cardiomyopathy (HCM), a disease of the sarcomere, is identified by mutations in MYBPC3 gene encoding cMyBP-C." (PMID 33330662, 2020). "Genetic testing discovered the prevalence of MYBPC3 and MYL2in patients with hypertrophic cardiomyopathy and AF." (PMID 33041871, 2020). "This includes the myosin binding protein C3 (MYBPC3) which has previously been implicated in the Mendelian cardiac muscle diseases, hypertrophic cardiomyopathy and dilated cardiomyopathy." (PMID 31235787, 2019). "We investigated the feasibility and efficacy of viral-mediated AON transfer in a Mybpc3-targeted knock-in (KI) mouse model of hypertrophic cardiomyopathy (HCM)." (PMID 23716398, 2013). "MYBPC3, which is a gene with a slight but consistent increase in expression over the trajectory, has been shown to support cardiomyocyte proliferation and is related to hypertrophic cardiomyopathy." (PMID 38177382, 2024). "Hypertrophic cardiomyopathy (HCM) is caused by myocardial hypertrophy, often due to mutations in cardiac sarcomere protein genes such as beta-myosin heavy chain (MYH7) and myosin-binding protein C (MYBPC3)." (PMID 39165751, 2024). "This suggests that the P161S mutation may lead to a shortened systole duration, potentially contributing to hypertrophic cardiomyopathy, as observed in MYBPC3 knockout mouse hearts." (PMID 39456977, 2024). "Discordant interpretations exist for 229 variations in Hypertrophic Cardiomyopathy, with the majority of these variations located in well-known cardiomyopathy-related genes such as MYBPC3 (68 variations), MYH7 (49 variations), TNNI3 (20 variations), or TNNT2 (20 variations)." (PMID 37946154, 2023). "The first patient is a female proband exhibiting hypertrophic cardiomyopathy (HCM) and biventricular heart failure carrying a truncating homozygous MYBPC3 variant c.1224-52G>A (IVS13-52G>A) and a novel homozygous variant (c.302A>G; p.Asn101Ser) in the SMYD1 gene." (PMID 36980931, 2023). "Only two individuals (2/309) had P/LP variants in multiple genes: one harbouring predisposition to familial hypercholesterolemia (FH) and long QT syndromes (PCSK9, KCNH2) and the other with predisposition to cancer and hypertrophic cardiomyopathy (SDHD, MYBPC3)." (PMID 36335097, 2022). "Here we investigated burst-like transcription and its consequences in cardiac tissue from Hypertrophic Cardiomyopathy (HCM) patients with heterozygous mutations in the sarcomeric proteins cardiac myosin binding protein C (cMyBP-C, MYBPC3) and cardiac troponin I (cTnI, TNNI3)." (PMID 36082122, 2022). "For example, a recent study proposed that an R495W mutation in cMyBP-C (encoded by MYBPC3), a myosin-associated protein located along the myosin thick-filament backbone in muscle, decreases its mechanical stability and causes hypertrophic cardiomyopathy." (PMID 36398718, 2022). "Of note, case 1 did display cardiac involvement and did not carry the MYBPC3 A31P variant causing hypertrophic cardiomyopathy in this breed." (PMID 36359052, 2022). "For example, variants in the myosin binding protein C3 (MYBPC3) gene region, which are common (2%-8%) in South Asian ancestry populations but rare (<0.1%) in European ancestry populations, are associated with an increased risk of hypertrophic cardiomyopathies." (PMID 35142634, 2022).
hypertrophic cardiomyopathy (continued). "For example, the three variants linked to multiple variables in the arrhythmia category (MYBPC3:c.3288G>A, MYBPC3:c.2308+18C>G and MYL2:c.132T>C) are in genes associated with hypertrophic cardiomyopathy (HCM), where arrhythmias are secondary to ventricular remodeling." (PMID 36008935, 2022). "The other nine (1–6 years of age; 4 females, 5 males) affected Sphynx cats did not have either the ALMS1 variants or the two known feline hypertrophic cardiomyopathy MYBPC3 mutations." (PMID 33639992, 2021). "Pathogenic splice acceptor variant c.26-2A > G in MYBPC3 (rs376395543) is associated with hypertrophic cardiomyopathy (VCV000042644.10) and is observed in six copies in non-Finnish Europeans (frequency 5.2 × 10–5) and one allele copy in Latino Americans." (PMID 34691145, 2021). "Hypertrophic cardiomyopathy (HCM) is an inherited disorder of the myocardium, and pathogenic mutations in the sarcomere genes myosin heavy chain 7 (MYH7) and myosin-binding protein C (MYBPC3) explain 60%–70% of observed clinical cases." (PMID 32344918, 2020). "Methods and Results: S100A4 mRNA and protein levels were analyzed in different models of cardiac pathology via quantitative RT-PCR and Western blot, showing a higher S100A4 steady-state protein concentration in hearts of Mybpc3-knock-in (KI) hypertrophic cardiomyopathy (HCM) mice." (PMID 30283351, 2018). "However, immunostaining showed few deposition of globotriaosylceramide in left ventricular myocardium, and gene mutations in the disease genes for hypertrophic cardiomyopathy (HCM), MYBPC3 and MYH6, were detected." (PMID 27160240, 2016). "Many people, even within the same family, with the same pathogenic MYBPC3 variant may have no or few symptoms, will never develop hypertrophic cardiomyopathy and are unaware that they have this genotype." (PMID 38752549, 2024). "For instance, approximately 6% of pathogenic variants in MYBPC3, a gene associated with hypertrophic cardiomyopathy, are non-canonical splice variants, including deep intronic variants, some of which may be more readily detected through ONT LRS enhanced intronic coverage." (PMID 41300778, 2025). "The present study comprised sarcomeric genotyping of the three most commonly involved sarcomeric genes: MYBPC3, MYH7, and TNNT2 in 192 unrelated Egyptian hypertrophic cardiomyopathy (HCM) index patients." (PMID 23233322, 2013). "In hypertrophic cardiomyopathy (HCM), MYBPC3, MYH7, PRKAG2, RAF1, and RBM20 were prevalent." (PMID 41341110, 2025). "In this study, isogenic iPSC lines were generated for a variant of unknown significance found previously in a patient with hypertrophic cardiomyopathy (HCM), p.N515del (c.1543_1545delAAC) in MYBPC3." (PMID 39684611, 2024). "In one family (family 3, MYBPC3) the phenotype was not quite as clear- only findings on cardiac MRI in one adult carrier were consistent with hypertrophic cardiomyopathy." (PMID 38740897, 2024). "Additionally, variants found in individuals of the cardiogenetics cohort were in genes: MYBPC3 and KCNH2, both consistent with the pathologies investigated: Arrhythmia and Hypertrophic cardiomyopathy." (PMID 35087072, 2022). "MYBPC3 mutations have been known to contribute hypertrophic cardiomyopathy (HCM); however, the role of the MYBPC3 p.Val895Met variant is not clear." (PMID 27182706, 2016).
cardiomyopathy (127 papers, 2011 to 2026). A disease of the heart muscle or myocardium proper. "Although MYBPC3 mutations are well known in other cardiomyopathies, they appear to be less common in DCM." (PMID 41374444, 2025). "We recreated their experiment in which they investigated a MYBPC3 intron mutation associated with cardiomyopathy." (PMID 40166201, 2025). "We recreated their experiment in which they investigated an MYBPC3 intron mutation associated with cardiomyopathy." (PMID 41165728, 2025). "Among the 50 unique cardiomyopathy genes with truncating mutations, MYBPC3, TNNT2, and phospholamban (PLN) exhibited a high ratio of cases compared to reference populations for HCM." (PMID 38406555, 2024). "Previously, we showed that a 25 bp deletion in the MYBPC3 (MYBPC3Δ25bp) gene affecting the C10 domain of the MYBPC3 protein is associated with cardiomyopathy." (PMID 38361607, 2024). "In particular, we have shown that the MYBPC3 25 bp deletion is common in human populations and is associated with cardiomyopathy that affects approximately 100 million people worldwide." (PMID 38361607, 2024). "Probands with HCM caused by a pathogenic deletion of exon 23-26 of MYBPC3 were identified through genetic screening using a gene panel encompassing 59 genes associated with cardiomyopathies in a single genetic center in Belgium." (PMID 38836037, 2024). "In the context of cardiomyopathies associated with MYBPC3, cardiac dysfunction predominantly arises from splicing abnormalities stemming from mutations at donor or acceptor sites or the insertion and deletion of intronic sequences." (PMID 38406555, 2024). "One patient with MYBPC3 mutation-positive was a 15-year-old boy, a case of myoclonus dystonia with a family history of cardiomyopathy and sudden cardiac death who had diffuse subendocardial enhancement on C MRI." (PMID 37679699, 2023). "Distal Arthrogryposis has been attributed to pathogenic variants in MYBPC1, and MYBPC3 is known to cause a series of cardiomyopathies, including HCM, DCM and congenital heart defects." (PMID 35832193, 2022). "cMyBP-C is a key regulator of cardiac contractility with more than 300 mutations in the MYBPC3 gene directly linked to the development of cardiomyopathy and heart failure." (PMID 35288601, 2022). "TTN, GAA, LAMA2, and MYBPC3 contained the most variants in the three subgroups which confirm the impact of these genes in the complex pathogenesis of cardiomyopathies and VT." (PMID 33552729, 2021). "Compound heterozygous or homozygous MYBPC3 mutations have also been shown to cause severe cardiomyopathy which was lethal in the first few weeks after birth." (PMID 33148509, 2021). "TTN, GAA, LAMA2 and MYBPC3 harbored the most variants in the three subgroups which confirm the high impact of these genes in complex pathogenesis of cardiomyopathies and VT demonstrated in previous studies." (PMID 33552729, 2021). "Case 4 had Arg160Trp-MYBPC3, AD inheritance of a cardiomyopathy-related gene variant suspected to be harmful by in silico analysis." (PMID 34728707, 2021). "Proband 30 had a second diagnosis—a frameshift variant in MYBPC3 associated with cardiomyopathies—that likely explained the proband’s significant heart failure requiring persistent afterload reduction." (PMID 33888711, 2021). "Rather, the increased frequency of this variant in South Asian cardiomyopathy cohorts reflects the enrichment of a derived haplotype, which bears both the common MYBPC3Δ25 variant and a rare pathogenic variant, MYBPC3 c.1224-52G>A." (PMID 32163302, 2020).
cardiomyopathy (continued). "C.927-2A>G in MYBPC3 (MAF = 0.18%) associates with cardiomyopathy, heart failure, ventricular tachycardia and atrial fibrillation (AF), and p.Arg721Trp (MAF = 0.34%) in MYH6 with sick sinus syndrome (SSS), AF and coarctation of the aorta." (PMID 31641117, 2019). "All patients with homozygous or compound heterozygous truncating pathogenic mutations in MYBPC3 reported so far (n = 21) were diagnosed with severe cardiomyopathy and/or died within the first few months of life." (PMID 30235249, 2018). "For instance, knockout of top Hridaya-predicted functional gene MYBPC3 causes increased heart-weight to body weight in mice, an important feature of cardiomyopathy." (PMID 29311597, 2018). "Twenty-six pathogenic or likely pathogenic mutations involved in 10 genes, and MYH7(8/26) and MYBPC3 (6/26) mutations accounted for more than 50% of the variants found in cardiomyopathy cases." (PMID 30165862, 2018). "The assay will provide quick and accurate prescreening of individuals at high risk for cardiomyopathies and allow for better clinical identification of 25-basepair deletion MYBPC3 carriers in large cohort epidemiological studies." (PMID 27990320, 2016). "No mutations were observed in the sequences of the genomic DNA in exons number 7, 16, and 18 of the gene MYBPC3, which is a major disease-causing gene in different cardiomyopathies, in the 50 patients with HCM enrolled in the study." (PMID 27956910, 2016). "Thus, thismolecular genetic mechanism is highly likely implicated in the pathogenesis ofHCM, given the established association between MyBPC3 mutations and thisspecific manifestation of cardiomyopathy." (PMID 40351682, 2025). "Similarly, mutations in the MYBPC3 gene are among the most common causes of various forms of cardiomyopathy." (PMID 40725155, 2025). "The roles of Gal-3 and titin in cardiac-related MYBPC3 gene mutations may provide further insights into the roles of these biomarkers in the pathophysiology of cardiomyopathies." (PMID 39619937, 2024). "Cardiomyopathy caused by variation in sarcomere genes such as MYBPC3 have been associated with an inflammatory phenotype and subsequent fibrosis, and whether the fibrosis detected by CMR in these patients is a result of inflammation remains to be proven." (PMID 35265679, 2022). "Hence, an MYBPC3-A74T mutation can reflect another cardiomyopathy phenotype, such as restrictive cardiomyopathy." (PMID 35400937, 2022). "Mutations of MYBPC3 gene are a major cause of human cardiomyopathy and associated HF." (PMID 34440529, 2021). "Pathogenic variants in NEBL and MYBPC3 have been associated with cardiomyopathies." (PMID 34816733, 2021). "In our cohort, three patients had variants identified in genes (ABCC9, FLNC, MYBPC3) that have associations with different cardiomyopathies and may contribute to the clinical phenotype in these families." (PMID 33302605, 2020). "Mutations in myosin-binding protein C cardiac isoform (MYBPC3), the accessory protein of the sarcomere A-band, have been found in various types of cardiomyopathy, however the relationship between these mutations and disease onset remains unknown." (PMID 30988697, 2019). "Therefore, the incorporation of a substrate with adjustable stiffness enabled assessment of tissue-level response to mechanical stress, highlighting the possible connection between onset of cardiomyopathy and mutations in MYBPC3." (PMID 30988697, 2019). "In addition to TTN and BAG3, MYBPC3 was present in the cardiomyopathy gene-set and harbored variants associated with sporadic DCM in our EWAS." (PMID 28296976, 2017). "A 25-basepair deletion variant of MYBPC3 occurs at high frequency in individuals of South Asian descent and is estimated to affect 55 million people worldwide, carrying an increased likelihood of cardiomyopathy." (PMID 27990320, 2016). "MYBPC3 is a major disease-causing gene in different cardiomyopathies." (PMID 27956910, 2016).